AREG (amphiregulin)
Diseases named in the same sentence as AREG in open-access papers (continued):
Sharing a sentence is not in itself a finding about the gene and the disease.
breast carcinoma (continued). "Given the induction by Pparγ1 of EphA2, Amphiregulin, Adam12 in the mammary tumors we sought to determine whether PPARγ1 directly interacted in the context of chromatin with these target genes." (PMID 33946495, 2021). "As zearalenone and apigenin activated ERs, we tested the potential effect of these molecules on the expression of endogenous E2-dependent genes, such as the chemokine CXCL12, the progesterone receptor (PgR), amphiregulin (AREG) and growth regulation in breast cancer 1 (GREB1)." (PMID 30678243, 2019). "Additionally, breast and colon cancer-EVs containing amphiregulin boosted invasiveness of both epithelial and breast cancer cells." (PMID 31141946, 2019). "In addition to breast cancer, AREG has been shown to play an important role in mammary gland development." (PMID 30367629, 2018). "Amphiregulin (AREG), a ligand of the epidermal growth factor receptor, is not only essential for proper mammary ductal development, but also associated with breast cancer proliferation and growth." (PMID 30367629, 2018). "We examined the role of AREG in breast cancer using the MMTV-PyMT (PyMT) model in AREG−/− mice." (PMID 30367629, 2018). "We have also discussed the possible impact of these variants on the methylation of ADAMTSL1, its interaction with other members of the ADAMTS gene family and their association with the expression of other biologically relevant genes such as AREG in the context of breast cancer prognosis." (PMID 29158497, 2017). "In addition, in patients with metastatic HER2-positive breast cancer receiving trastuzumab plus taxane, the progression-free survival was significantly shortened in patients with high serum concentrations of AREG." (PMID 27933395, 2017). "Furthermore, we demonstrated cancer-derived AREG partially promoted breast cancer growth and migration via an autocrine AREG/EGFR signaling pathway." (PMID 27765922, 2016). "An invasive role of tumor-derived exosomes has also been shown by work from Higginbotham et. al which identified exosomes derived from cells stably expressing amphiregulin, an epidermal growth factor family member, increased invasiveness of “recipient” breast cancer cells by five-fold." (PMID 25798887, 2015). "Previous researches also showed that the downstream factors of ErbB pathway, such as MMP-9, uPA, EMMPRIN, and PAI-1, could be induced by AREG in head and neck cancer, breast cancer, and malignant mesothelioma cell lines." (PMID 25762634, 2015). "Nonetheless, AREG promotes the migration of tumor cells and its overexpression has been observed in several cancer tissues such as colorectal, gastric, pancreatic and breast cancer." (PMID 26503469, 2015). "As Amphiregulin is proteolytically released from the surface of breast cancer cells, we investigated the levels of Amphiregulin in the serum of breast cancer patients and cancer-free women to evaluate its potential utility as a breast cancer biomarker." (PMID 24010672, 2013). "The role of amphiregulin in breast cancer cells has been suggested in previous studies." (PMID 23844004, 2013). "Notably, amphiregulin significantly protected the breast cancer cells from cell death induced by detachment from their normal extracellular matrix (anoikis)." (PMID 24068959, 2013). "Therefore, we sought to compare the effects of two other EGFR ligands relevant to mammary gland development and breast cancer, AREG and TGFα, on K5+K19- hMEC cell differentiation." (PMID 24124521, 2013). "Median Amphiregulin levels were significantly higher than found in the cancer-free controls in the Cohort 1 ER + patients (P = 0.0068) and in the Cohort 2 ER + patients (P = 0.019) suggesting a shift towards Amphiregulin positivity in women with breast cancer." (PMID 24010672, 2013). "Amphiregulin overexpression has also been demonstrated in breast cancer." (PMID 23844004, 2013). "Thus, we provide evidence that Monad prevents breast cancer cell invasion by degrading amphiregulin mRNA." (PMID 23844004, 2013).
breast carcinoma (continued). "To address this issue we correlated amphiregulin expression levels with the Cisplatin resistant state of a collection of human breast cancer cells and found a correlation which demonstrates that breast cancer cells use amphiregulin as a survival signal to resist exposure to Cisplatin." (PMID 21967738, 2011). "The study, which included 311 early-stage breast cancer patients, investigated associations between preoperative serum levels of EGFR and EGFR ligands (epidermal growth factor, heparin-binding epidermal growth factor (HBEGF), amphiregulin, transforming growth factor-α and betacellulin) and survival." (PMID 33024132, 2020). "Previous studies have reported that AREG expression is upregulated by estrogen both in vitro and in vivo, and that high AREG expression is more prevalent in human ER+ breast cancers than ER- breast cancers, suggesting that AREG upregulation may be associated with increased ER+ breast cancer risk." (PMID 31059536, 2019). "Moreover studies have reported that most malignant breast cancer cell lines express a high level of AREG, suggesting that AREG may promote metastasis." (PMID 26503469, 2015). "Considering that amphiregulin has been proposed as a biomarker for breast cancer, understanding Monad-amphiregulin axis in breast cancer may lead to the development of additional targeted agents to suppress this axis, and result in improved treatments for metastatic breast cancer." (PMID 23844004, 2013). "AREG knockdown decreased the migration distance of T47D and MCF7 breast cancer cells to 18.1 ± 3.8 pixels and 27.1 ± 2.5 pixels, respectively." (PMID 40422206, 2025). "The level of AREG mRNA expression in both T47D and MCF7 breast cancer cells was increased by E2 CM treatment." (PMID 40422206, 2025). "AREG, a member of the EGF family, was first identified in the supernatants of phorbol myristate acetate-treated human breast cancer cells MCF-7 in 1988." (PMID 39451251, 2024). "The first of these databases was the Molecular Taxonomy of Breast Cancer International Consortium (METABRIC) database, which shows increased expression of AREG in E545K mutant samples with an increased difference within the luminal B subtype." (PMID 38802751, 2024). "AREG has been previously and independently established as a signaling molecule required for the growth of PIK3CA-mutant breast cancer cells." (PMID 38802751, 2024). "The top five genes (NAT1, PPM1H, AREG, ACSS1, CXCL1) with the greatest differences in Z-scores were evaluated in the PIK3CA mutant breast cancer samples from TCGA." (PMID 38802751, 2024). "Similar to AREG-targeted mAbs, EREG-targeted mAbs were shown to synergize with mitoxantrone in mouse models implanted with prostate or breast cancer cells combined with stromal cells." (PMID 40727266, 2024). "Previously, ADAMTS1 was reported to promote metastasis of murine breast cancer through activating EGFR by shedding HB-EGF and amphiregulin." (PMID 38263290, 2024). "AREG is also secreted by TME cells, including Tregs, thereby promoting breast cancer pulmonary metastasis." (PMID 37563650, 2023). "EVs from the TNBC cells MDA–MB–231 were shown to be enriched with extracellular growth factor receptor (EGFR) ligands, such as amphiregulin (AREG), which promote the invasiveness of recipient breast cancer cells, thereby being considered a biomarker for TNBC." (PMID 37835573, 2023). "AREG is involved in regulating the proliferation and migration of erbB2- and HER2-positive breast cancer cells." (PMID 37604948, 2023). "Analysis of lung Vγ4+ and Vγ6+ cells in mammary tumor-conditioned lungs revealed that inhibition of ICOS, PD-1, or TIM-3 failed to alter the proportion of cells expressing IL-17A, IL-17F, TIM-3, or AREG." (PMID 36480166, 2023). "AREG (amphiregulin), a member of the EGF family and a ligand for EGFR or TNF-alpha receptor, is involved in the initiation and progression of breast cancer." (PMID 35681777, 2022).
breast carcinoma (continued). "In women, amphiregulin expression is elevated in human ductal carcinomas in situ (DCIS) compared to normal mammary tissues, as well as in primary infiltrating breast carcinomas, indicating it is an early event in human breast cancer." (PMID 31355130, 2019). "We crossed AREG-null (AREG−/−) mice with the murine luminal B breast cancer model, MMTV-PyMT (PyMT), to generate spontaneous breast tumors that lack AREG (AREG−/− PyMT)." (PMID 30367629, 2018). "Amphiregulin (AREG), a ligand of EGFR, has been found to be overexpressed in estrogen receptor (ER)-positive breast cancer." (PMID 30367629, 2018). "Recent data reported that exosomes released by colon and breast cancer cells contained the EGFR-ligand, Amphiregulin, and AREG-exosomes increased invasiveness of recipient cancer cells." (PMID 28600504, 2017). "To determine the effects of AREG signaling on breast cancer cells, we subsequently treated MCF7-shCTL and MCF7-shGPR81 cells with AREG." (PMID 27765922, 2016). "Moreover, increased AREG expression may be linked to cisplatin resistance in mammary cancer and HepG2 hepatoma cell lines, but not in pulmonary cancer or HNSCC cell lines." (PMID 27669890, 2016). "Other studies have previously identified overexpression of EGFR, and its ligand, amphiregulin (AREG), in young breast cancer patients." (PMID 26251034, 2015). "Amphiregulin, a ligand of the epidermal growth factor receptor (EGFR), was initially identified as a secreted factor in the ERα-positive MCF7 breast cancer cell line, and was shown to be estrogen-responsive in these cells." (PMID 24010672, 2013). "Consistent with PRL-enhancement of E2-driven proliferation of breast cancer cells, select PRL-modulated transcripts displayed positive co-regulation by E2, including the growth factors EREG and AREG." (PMID 23758962, 2013). "To further validate our cell line as a new model for breast cancer studies, we selected HBEGF and AREG genes known to play important role in breast tumorigenesis and proposed as therapeutic targets for various human cancers including breast cancer." (PMID 23029355, 2012). "STAT1-/- ERα+ mammary tumors also showed elevated transcription of genes characteristic of luminal breast cancers (for example, keratin 8, keratin 18, XBP1, GATA3, MYB, AREG, and FOXA1)." (PMID 22264274, 2012). "Most importantly, STAT1-/- mammary tumors express elevated levels of ERα, PR, GATA3, AREG, XBP1, and FOXA1, all of which are regulated by the transcriptional control of ERα." (PMID 22264274, 2012). "Therefore, the induction of AREG by E2 plays an important role in cell proliferation and migration in EGFR+ and ER+ breast cancer cells." (PMID 40422206, 2025). "Furthermore, suppressing the AREG/EGFR signaling pathway can be a fundamental therapeutic strategy for EGFR+ and ER+ breast cancers when combined with classic chemotherapy." (PMID 40422206, 2025). "In the absence of AREG expression, cell growth was slowed, and the invasion of inflammatory cells into breast cancer cells was reduced but not completely inhibited." (PMID 40422206, 2025). "ADAM17 is involved in the process of breast cancer development and progression, shedding ligands such as TGF-α, AREG, EGFR ligands, and betacellulin and then activating EGFR which promotes breast cancer cell growth and invasion through the PI3K/AKT and Ras/MAPK signaling pathways." (PMID 41050403, 2025). "We found that AREG expression in the serum of tamoxifen-treated ER+ breast cancer patients increased in a stage-dependent manner, although there were no stage 4 breast cancer patients in our sample." (PMID 40422206, 2025). "Therefore, AREG+, IL7R+ and VCAM1+ innate lymphoid cells can help determine prognosis for breast cancer patients." (PMID 36497286, 2022). "Similar to amphiregulin and TGF-α, EGF is reported to promote breast tumorigenesis through EGFR activation, and inhibition of EGF/EGFR signaling has been shown to exert anti-tumor effects for breast cancer." (PMID 31532771, 2019).
breast carcinoma (continued). "The results of our study demonstrate that AREG increases intracellular MMP-9 and -2 levels both under control conditions and upon infection, which is consistent with a previous study that showed AREG to upregulate MMP-9 in breast cancer cells." (PMID 30524196, 2018). "The same dataset was also used previously to demonstrate the impact of abnormal expression of TACE, TGFA, and AREG, which were shown to play important roles in the HMT3522 series of the breast cancer cells grown in the 3D culture, on the survival of the same cohort of the breast cancer patients." (PMID 25057922, 2014). "Of these, we focused on amphiregulin, because its probe signal was markedly up-regulated both in RPAP3 and PIH1D1 siRNA-treated cells; moreover, amphiregulin has been reported to have high levels of expression in hormone therapy-resistant breast cancer cells." (PMID 23844004, 2013). "We have demonstrated that Amphiregulin is released from the cell surface by TACE/ADAM17 and drives EGFR pathway activation in several breast cancer cell lines suggesting that inhibiting the proteolytic production of EGFR ligands is a new mechanism by which to target EGFR signaling in cancer." (PMID 24010672, 2013). "Comparing the expression of these genes in breast carcinomas and normal breast tissue, neither AREG nor GREB1 are differentially expressed between normal breast tissue and breast carcinomas." (PMID 21812955, 2011). "Interestingly, both AREG and GREB1 were up-regulated in ER+ breast carcinomas of younger (< 45 years) compared with older (> 70 years) women in a previous publication." (PMID 21812955, 2011). "Among top downregulated genes, amphiregulin (AREG) is involved in EMT and growth in different types of cancer, including PDAC, while Adhesion G Protein-Coupled Receptor F1 (ADGRF1) has an important role in inducing quiescence and chemoresistance in breast cancer." (PMID 37174038, 2023). "Interestingly, it was reported that HIF2α enhances autocrine growth signaling through AREG and EGFR/ErbB4 expression in breast cancer cell lines, strengthening this hypothesis." (PMID 36230857, 2022). "Similarly, EVs secreted by fibroblasts support colorectal cancer cell proliferation, probably through the transfer of amphiregulin, and FAK signaling in CAFs regulates the abilities of CAF-derived exosomes to induce breast cancer cell migration and ultimately metastasis." (PMID 34021474, 2021). "Analysis of the secreted “cytokine signature” in the extracellular milieu of luminal-like ER+ breast cancer cells exhibiting an HRG-driven endocrine-resistant phenotype revealed the differential upregulation of three well-known regulators of ERα activity, namely, uPAR, amphiregulin, and IL-8." (PMID 33086721, 2020). "Importantly, our major novel finding revealed that AREG is a critical mediator of BPAF-induced ER-RTK crosstalk and is essential for the cancer-promoting effects of BPAF in our in vitro cell line models of ER+ breast cancer." (PMID 31059536, 2019). "Hence, amphiregulin levels are not overexpressed in the early stages of Neu tumorigenesis (pre-hyperplastic and hyperplastic lesions), unlike in other transgenic mouse mammary cancer models." (PMID 31355130, 2019). "In cell culture, breast cancer cells with secondary resistance to trastuzumab displayed an up-regulation of mRNA expression for EGF, TGFα, HB-EGF and heregulin, while the expression of AREG mRNA was downregulated and the expression of epiregulin and betacellulin mRNA was unchanged." (PMID 27933395, 2017). "Moreover, high expression of EPAS1/HIF2α, AREG and WISP2 is linked to improved survival in breast cancer; glyceollin treatment does not affect EPAS1/HIF2α expression in the absence of E2 treatment and even partially restores expression in E2-treated cells." (PMID 28666461, 2017). "Thus, increased AREG expression may increase cisplatin resistance in HNSCC, as reported for mammary cancer cell lines." (PMID 27669890, 2016).
breast carcinoma (continued). "Thus, AREG appears to be an important target gene for E2 and T3 in MCF-7 breast cancer cells." (PMID 24587767, 2014). "Considering the established role for AREG as a paracrine mediator of E2-induced proliferation of luminal breast epithelial cells during pubertal growth, AREG may be directly involved in PRL stimulation of E2-driven growth of human breast cancer." (PMID 23758962, 2013). "The ability of WT1–ZF to reduce/block the expression of genes such as c-myc, Bcl-2, AREG and WT1 itself, genes important for the survival and proliferation of breast cancer cells, raised the possibility that WT1–ZF could impair the growth of breast cancer cells." (PMID 17634147, 2007). "Therefore, we suggest that AREG acts as an intermediary between EGFR and ER and targeting both ERs and EGFRs through combination therapy could prevent tumor progression in EGFR+ ER+ breast cancer patients." (PMID 40422206, 2025). "This is also supported by the observation that the expression of AREG and CXCL1 did not correlate in breast cancer, while they highly correlated in prostate cancer." (PMID 35998057, 2022). "We subsequently performed an angiogenesis protein array and found that CXCL16, amphiregulin and tissue inhibitor of metalloproteinases (TIMP1) were expressed at high levels in the TN but not the ER+ breast cancer CAF supernatants." (PMID 27725631, 2016). "Consistent with a central role for the breast cancer cell EGFR in the stimulation of osteoclastogenesis, the addition of exogenous AREG to co-cultures containing shEGFR-MDA-231cell failed to induce increased numbers of the bone resorbing cells." (PMID 22276166, 2012).